LINC02362 (long independently transcribed non-coding RNA 2362)
Synonyms: PLUM
Gene: Long non-coding RNA gene on chromosome 4 (184,365,180 to 184,382,416, reverse strand). Ensembl gene ENSG00000249096.
Diseases named in the same sentence as LINC02362 in open-access papers:
LINC02362 is named in the same sentence as 4 diseases in open-access papers, as found by Europe PMC text mining. Sharing a sentence is not in itself a finding about the gene and the disease.
LINC02362 shares sentences with these, for which no sentence is quoted: cancer (1 paper); multiple myeloma (1); myeloma (1); tumor (1).